CCDC63 (coiled-coil domain containing 63)
Description:
Plays a role in spermiogenesis. Involved in the elongation of flagella and the formation of sperm heads.
Synonyms: ODA5; FLJ35843
Tractability: No criterion of Open Targets' tractability assessment is met for any kind of drug.
Gene: Protein-coding gene on chromosome 12 (110,846,769 to 110,907,535, forward strand). Ensembl gene ENSG00000173093.
Subcellular location (Human Protein Atlas): Nucleoplasm; Principal piece; Cell Junctions
Gene Ontology:
Biological process: cilium movement; outer dynein arm assembly; spermatid development
Cellular component: axoneme
Genetic constraint (gnomAD): Loss-of-function variants: 55 observed, 65.5 expected, observed/expected ratio (o/e) 0.84, 90% interval 0.68 to 1.05. The upper end of that interval is the gene's LOEUF score, 1.05, which puts it in group 4 of 6, group 1 being the genes least tolerant of losing a copy. Missense variants: 636 observed, 719.63 expected, observed/expected ratio (o/e) 0.88, 90% interval 0.83 to 0.94. Synonymous variants: 253 observed, 281.98 expected, observed/expected ratio (o/e) 0.9, 90% interval 0.81 to 1.
Homologues: Orthologues: chimpanzee CCDC63 (99% identical), macaque CCDC63 (94% identical), guinea pig CCDC63 (77% identical), dog CCDC63 (76% identical), pig CCDC63 (76% identical), rabbit CCDC63 (75% identical), rat Ccdc63 (70% identical), Drosophila melanogaster Ccdc114 (20% identical). Paralogues in human: ODAD1 (24% identical), ODAD3 (13% identical), TMEM141 (3% identical).
Diseases named in the same sentence as CCDC63 in open-access papers:
CCDC63 is named in the same sentence as 8 diseases in open-access papers, as found by Europe PMC text mining. Sharing a sentence is not in itself a finding about the gene and the disease. The quoted sentences say what the papers report.
COVID-19 (1 paper, 2024). A disease caused by infection with severe acute respiratory syndrome coronavirus 2. "Taken together, there is evidence suggestive of molecular mimicry between the immunologically important Spike protein fusion peptide and the muscle proteins TRIM63 and CCDC63 alongside associations with muscular symptoms post-COVID-19 and COVID-19 severity." (PMID 39414823, 2024).
dyslipidemia (1 paper, 2026). "This study investigated the synergistic impact of CCDC63 (coiled-coil domain containing 63) polymorphisms and alcohol intake on dyslipidemia risk within a Korean cohort." (PMID 41828368, 2026).
Infertility (1 paper, 2024). "Research has shown that the removal of CCDC63 leads to infertility in male mice, primarily due to the shortening of flagella." (PMID 38750582, 2024).
cancer (1 paper, 2021). A tumor composed of atypical neoplastic, often pleomorphic cells that invade other tissues. "In contrast, in silico analysis shows that CCDC63 expression is low and conserved between cancer and noncancer tissues." (PMID 34885177, 2021).
CCDC63 also shares sentences with these, for which no sentence is quoted: Hypertension (1 paper); hypertriglyceridemia (1); hyperuricemia (1); oral cancer (1).